PKD1 (polycystin 1, transient receptor potential channel interacting)
Diseases named in the same sentence as PKD1 in open-access papers (continued):
Sharing a sentence is not in itself a finding about the gene and the disease.
autosomal dominant polycystic kidney disease (continued). "In this report we describe the sea urchin SpREJ gene family that are members of the larger PKD1 gene family, whose mutations in humans are associated with autosomal dominant polycystic kidney disease." (PMID 17629917, 2007). "For instance, Autosomal Dominant Polycystic Kidney Disease (ADPKD) is primarily attributed to pathogenic variants in the PKD1 and PKD2 genes, while Marfan syndrome and Neurofibromatosis type 1 (NF1) are mainly associated with the FBN1 and NF1 genes, respectively." (PMID 41411243, 2025). "Here, we analyzed orexin-A levels as well as the incidence of SNPs in the hypocretin neuropeptide precursor (HCRT) and its receptors, HCRTR1 and HCRTR2, in 64 patients affected by autosomal dominant polycystic kidney disease (ADPKD) bearing truncating mutations in the PKD1 or PKD2 genes." (PMID 38892431, 2024). "Autosomal dominant polycystic kidney disease is caused by mutations in PKD1 or PKD2 genes." (PMID 37028763, 2023). "In South Africa, the 3′ region of PKD1 mutation is the molecular genetic basis of autosomal dominant polycystic kidney disease (ADPKD) associated with polycystin-1 and polycystin-2 dysfunction implicated in tubulogenesis changes reported in South Africa, Tunisia, Senegal, Sudan, and Congo." (PMID 36672600, 2022). "The same disease can be caused by different genes, and this could influence the outcome (i.e., mutations in PKD1 are associated with earlier ESRD than PKD2 in autosomal dominant polycystic kidney disease [ADPKD]); this is known as genetic heterogeneity." (PMID 35207681, 2022). "Mutations in the PKD1 gene could also result in autosomal dominant polycystic kidney disease and loss of PKD1 impaired lysosomal activity in a calpain-dependent manner." (PMID 35337339, 2022). "Mouse models deficient for Pkd1, which encodes the protein polycystin-1 and is commonly mutated in autosomal dominant polycystic kidney disease, have skeletal abnormalities, and isolated MSCs and primary osteoblasts have a decreased osteogenic but increased adipogenic potential." (PMID 34759842, 2021). "Digenic inheritance has also already been reported to have a prognostic role in other kidney diseases, such as congenital nephrotic syndrome (mutations in NPHS1 and NPHS2), autosomal dominant polycystic kidney disease (mutations in PKD1 and PKD2) and Bartter's syndrome." (PMID 33330536, 2020). "Another case is that the autosomal dominant polycystic kidney disease in humans often inherits heterozygous loss-of-function mutations in either PKD1 (polycystic kidney disease-1) or PKD2 (polycystic kidney disease-2), while the mice displays only very mild cystic disease in the same situation." (PMID 32586408, 2020). "Mutations in PKD1 can cause autosomal dominant polycystic kidney disease (OMIM #173900)." (PMID 31451708, 2019). "Autosomal dominant polycystic kidney disease is defined as an inherited disorder characterized by renal cyst formation due to mutations in the PKD1 or PKD2 gene, whereas tuberous sclerosis complex is an autosomal dominant neurocutaneous syndrome caused by mutation or deletion of the TSC2 gene." (PMID 31870441, 2019). "Most cases of autosomal dominant polycystic kidney disease (ADPKD) are due to mutations in PKD1." (PMID 31822676, 2019). "PKD2 and PKD1 genes are mutated in human autosomal dominant polycystic kidney disease." (PMID 29899465, 2018). "Most notably, this gene/protein family is named after PKD because mutations in either PKD1 or PKD2 account for all of the known forms of Autosomal Dominant Polycystic Kidney Disease (ADPKD), which is the most common genetic cause and the fourth most common cause of kidney failure." (PMID 28271061, 2017). "Indeed, β-catenin is necessary for proper regulation of the PKD1 promoter, that is mutated in 85% of patients with Autosomal Dominant Polycystic Kidney Disease (ADPKD)." (PMID 27668431, 2016).
autosomal dominant polycystic kidney disease (continued). "Mir-1225 targets the polycystic kidney disease gene, PKD1, which is frequently mutated in autosomal dominant polycystic kidney disease; thus, miR1225 may affect the progression of this disease." (PMID 26208314, 2015). "Furthermore, Polycystin-1 − the product of the PKD1 gene mutated in ~ 85% of individuals with autosomal dominant polycystic kidney disease − activates the Calcium/NFAT pathway, components of which can be detected in late gestation and adult kidney." (PMID 21295565, 2011). "Polycystin-1 (PC-1), the product of the PKD1 gene, mutated in the majority of cases of Autosomal Dominant Polycystic Kidney Disease (ADPKD), is a very large (∼520 kDa) plasma membrane receptor localized in several subcellular compartments including cell-cell/matrix junctions as well as cilia." (PMID 19774080, 2009). "PKD1 heterozygosity underlies autosomal dominant polycystic kidney disease (ADPKD), a disorder affecting nearly 12 million people worldwide, where reduced PKD1 dosage drives progressive cyst formation and kidney failure." (PMID 41558825, 2026). "Autosomal dominant polycystic kidney disease (ADPKD), caused by mutations in PKD1 or PKD2, is characterized by progressive and exponential enlargement of renal and hepatic cysts." (PMID 41677660, 2026). "Autosomal Dominant Polycystic Kidney Disease (ADPKD), caused by pathogenic variants in PKD1 and PKD2, is the most common monogenic cause of kidney failure." (PMID 41006799, 2026). "Autosomal dominant polycystic kidney disease (ADPKD), caused by PKD1/PKD2 mutations, features renal and extrarenal manifestations including valvulopathies and left ventricular hypertrophy (LVH), which increase mortality." (PMID 41195291, 2025). "Autosomal dominant polycystic kidney disease (ADPKD) is usually caused by variants in the PKD1 and PKD2 genes." (PMID 39883360, 2025). "Autosomal Dominant Polycystic Kidney Disease (ADPKD) is a systemic ciliopathy resulting from loss-of-function mutations in the PKD1 and PKD2 genes, which encode polycystin-1 (PC1) and polycystin-2 (PC2), respectively." (PMID 40801635, 2025). "Autosomal dominant polycystic kidney disease (ADPKD) is the more prevalent form, subdivided into the PKD1 and PKD2 variants." (PMID 40710847, 2025). "In some patients, the co-occurrence of TSC and autosomal dominant polycystic kidney disease (ADPKD) is caused by the TSC2/PKD1 contiguous gene syndrome (CGS)." (PMID 41227201, 2025). "Polycystin-1 (PC1) is the protein product of the PKD1 gene whose mutation causes autosomal dominant Polycystic Kidney Disease (ADPKD)." (PMID 39373641, 2024). "Patients with autosomal dominant polycystic kidney disease (ADPKD), a genetic disease due to mutations of the PKD1 or PKD2 gene, show signs of complement activation in the urine and cystic fluid, but their pathogenic role in cystogenesis is unclear." (PMID 38912583, 2024). "In autosomal dominant polycystic kidney disease (ADPKD) with germline mutations in a PKD1 or PKD2 gene, innumerable cysts develop from tubules, and renal function deteriorates." (PMID 38474184, 2024). "PKD1 is the most common pathogenic gene in autosomal dominant polycystic kidney disease (ADPKD) and PKD1 mutations have recently been recognized as biomarkers of ADPKD that can predict renal prognosis." (PMID 39556225, 2024). "To investigate whether the cysts were formed due to uncontrolled proliferation, as it is seen in autosomal dominant polycystic kidney disease with mutations PKD1 and PKD2 genes, we assessed Ki67 staining in the epithelial cells of proximal and distal tubules and found no significant changes." (PMID 39417621, 2024). "Autosomal dominant polycystic kidney disease (ADPKD) is commonly caused by PKD1, and mosaic PKD1 variants result in milder phenotypes." (PMID 38548773, 2024).
autosomal dominant polycystic kidney disease (continued). "Autosomal dominant polycystic kidney disease (ADPKD), caused by mutations in the polycystin-1 (PKD1) or polycystin-2 (PKD2) genes, is the most common life-threatening monogenic disease, affecting at least 1:1,000 individuals worldwide." (PMID 38095025, 2024). "Autosomal dominant polycystic kidney disease (ADPKD) is the most common genetic disease, which is caused by mutations in PKD1 and PKD2 genes, encoding for polycystin-1 and polycystin-2 proteins, respectively." (PMID 39456148, 2024). "Mutations in PKD1 or PKD2 cause autosomal dominant polycystic kidney disease (ADPKD), which is characterized by continued enlargement of fluid filled cysts within the kidney and other organs." (PMID 39085216, 2024). "Autosomal dominant polycystic kidney disease (ADPKD) is a hereditary kidney disease that is caused by mutation in polycystic kidney disease-1 (PKD1) gene or polycystic kidney disease-2 (PKD2) gene." (PMID 39172111, 2024). "A member of the wider group of ciliopathic disorders, autosomal dominant polycystic kidney disease (ADPKD) is caused primarily by mutations in the PKD1 or PKD2 genes, encoding the ciliary proteins polycystin 1 (PC1) and polycystin 2 (PC2), respectively." (PMID 38846086, 2024). "Autosomal dominant polycystic kidney disease (ADPKD) is one of the causes of end-stage renal disease and is caused by a polycystic protein-1 (PKD1) or PKD2 gene mutation." (PMID 37739961, 2023). "PKD1 is the most commonly mutated gene causing autosomal dominant polycystic kidney disease (ADPKD)." (PMID 37540694, 2023). "Autosomal dominant polycystic kidney disease (ADPKD) is the most common hereditary renal disease, and it is typically caused by PKD1 and PKD2 heterozygous variants." (PMID 37628640, 2023). "Autosomal dominant polycystic kidney disease (ADPKD), due to pathogenic variants in PKD1 or PKD2 genes, is generally an adult-onset disorder which commonly progresses to kidney failure." (PMID 40225160, 2023). "Autosomal dominant polycystic kidney disease (ADPKD), associated with mutations disabling the PKD1 gene, affects as many as 1 in 1000." (PMID 37542051, 2023). "Autosomal dominant polycystic kidney disease (ADPKD): ADPKD is the most common inherited progressive renal disease caused by the mutation of two major genes, PKD1 and PKD2, and the rare genes, GANAB and DNAJB11." (PMID 37445416, 2023). "Autosomal dominant polycystic kidney disease (ADPKD) is the most common monogenic cause of kidney failure in adults and is due to pathogenic variants in either PKD1 or PKD2." (PMID 37507763, 2023). "Mutations in PKD2 and PKD1 cause autosomal dominant polycystic kidney disease (ADPKD), a relatively common genetic nephropathy, wherein tubular epithelial cells proliferate to form cysts, ultimately resulting in renal failure." (PMID 38283366, 2023). "Autosomal dominant polycystic kidney disease (ADPKD) is mainly caused by mutations in two main genes, PKD1 (OMIM#: 601313) and PKD2 (OMIM#: 173910)." (PMID 35327948, 2022). "Autosomal dominant polycystic kidney disease (ADPKD) is the most common form of hereditary cystic kidney disease, affecting one in 1000–2500 individuals and is mainly caused by mutations in the PKD1 (78%) and PKD2 (15%) genes." (PMID 36362756, 2022). "Previous studies have identified PKD1 mutations in autosomal dominant polycystic kidney disease (ADPKD)." (PMID 35620448, 2022). "So far, PKD1 mutations were reported to be associated with autosomal dominant polycystic kidney disease (ADPKD, MIM 173900), which was featured by dilatation of the renal tubules leading to cyst formation and progressive renal failure." (PMID 35620448, 2022). "PC1 is encoded by polycystic kidney disease 1 (PKD1), and PKD1 mutations causes Autosomal dominant polycystic kidney disease (ADPKD)." (PMID 36309681, 2022).
autosomal dominant polycystic kidney disease (continued). "Autosomal dominant polycystic kidney disease (ADPKD) is caused by mutations in the PKD1 or PKD2 gene which encodes membrane receptor PKD1 and cation channel PKD2, respectively." (PMID 36035467, 2022). "Autosomal dominant polycystic kidney disease (ADPKD), among the most common human genetic conditions and a frequent etiology of kidney failure, is primarily caused by heterozygous PKD1 mutations." (PMID 35965273, 2022). "Autosomal dominant polycystic kidney disease (ADPKD, caused by variants in PKD1 and PKD2) is the most common inherited kidney disorder, is the fourth leading cause of chronic kidney disease, and is often not diagnosed until later stages of the disease." (PMID 34385667, 2021). "Autosomal dominant polycystic kidney disease (ADPKD) is caused by mutations in PKD1 or PKD2, and is the most common inherited kidney disorder that leads to end-stage renal disease at a prevalence of ∼1:1000." (PMID 34739029, 2021). "Downregulation of YAP/TAZ or c-Myc by inhibiting RhoA suppresses cystogenesis in a mouse autosomal dominant polycystic kidney disease model resulting from Pkd1 deficiency, and the G-protein-coupled receptor (GPCR) signaling could act through RhoA to regulate the Hippo-YAP pathway." (PMID 34365464, 2021). "Autosomal dominant polycystic kidney disease (ADPKD) is due to germ-line variants, predominantly in either PKD1 (85%) or PKD2 (15%), encoding the polytopic integral membrane, polycystin-1, and the calcium transient receptor channel, polycystin-2, respectively." (PMID 34638853, 2021). "Autosomal dominant polycystic kidney disease (ADPKD) is caused by loss of function of PKD1 (polycystin 1) or PKD2 (polycystin 2)." (PMID 34199520, 2021). "Autosomal dominant polycystic kidney disease (ADPKD) is caused by mutations in PKD1 or PKD2 gene and is the most common monogenic kidney disorder." (PMID 33809516, 2021). "Autosomal dominant polycystic kidney disease (ADPKD) is the leading genetic disease associated with end-stage renal disease and is caused by loss-of-function mutations in either PKD1 or PKD2." (PMID 34733559, 2021). "The autosomal dominant polycystic kidney disease (ADPKD) is mainly caused by the mutations in the PKD1 or PKD2 genes." (PMID 32823757, 2020). "Autosomal Dominant Polycystic Kidney Disease (ADPKD) is one of the most common causes of end-stage renal failure, caused by mutations in PKD1 or PKD2 genes." (PMID 31879244, 2020). "Autosomal Dominant Polycystic Kidney Disease (ADPKD) occurs due to mutations in Pkd1 or Pkd2 and is the most prevalent monogenic human disease worldwide, affecting 1 in 400–1000 individuals." (PMID 32364494, 2020). "Autosomal dominant polycystic kidney disease (ADPKD) is the most common (1:1000) adult-onset genetic chronic kidney disease (CKD) caused by variants in either PKD1, PKD2 or, rarely, other genes." (PMID 33147804, 2020). "However, in animal models of autosomal dominant polycystic kidney disease, a major disease caused by mutations in the polycystin genes (Pkd1 or Pkd2), primary cilia ablation or acceleration of deciliation suppresses cystic growth, whereas deceleration of deciliation enhances cystogenesis." (PMID 32651191, 2020). "Autosomal dominant polycystic kidney disease (ADPKD), the predominant type of inherited kidney disorder, occurs due to PKD1 and PKD2 gene mutations." (PMID 32957937, 2020). "Autosomal dominant polycystic kidney disease (ADPKD), which is defined as an inherited disorder characterized by renal cyst formation, is caused by dysfunction of polycystin 1 or polycystin 2, which leads to mutations in the PKD1 or PKD2 gene, respectively." (PMID 31870441, 2019). "Approximately 30% of Persian cats have a c.10063C > A variant in polycystin 1 (PKD1) homolog causing autosomal dominant polycystic kidney disease (ADPKD)." (PMID 31299928, 2019).
autosomal dominant polycystic kidney disease (continued). "Autosomal dominant polycystic kidney disease (ADPKD), caused by mutations in either PKD1 or PKD2 genes, is one of the most common human monogenetic disorders and the leading genetic cause of end-stage renal disease." (PMID 31515477, 2019). "Autosomal dominant polycystic kidney disease (ADPKD) is the consequence of a heterozygous mutation in one of two genes: PKD1 on chromosome 16, in 80-85% of cases, or PKD2 on chromosome 4." (PMID 31309115, 2019). "Autosomal dominant polycystic kidney disease (ADPKD) is the most common genetic renal disease, caused in the majority of the cases by a mutation in either the PKD1 or the PKD2 gene." (PMID 31773180, 2019). "Mutations in the corresponding genes, Pkd1 and Pkd2, have been associated with autosomal dominant polycystic kidney disease (ADPKD)." (PMID 29468160, 2018). "Autosomal dominant polycystic kidney disease (ADPKD), the commonest inherited kidney disease, is generally caused by heterozygous mutations in PKD1, PKD2, or GANAB (PKD3)." (PMID 30333007, 2018). "Autosomal dominant polycystic kidney disease (ADPKD) is a common genetic kidney disease resulting from mutations of PKD1 or PKD21." (PMID 28769124, 2017). "Autosomal dominant polycystic kidney disease (ADPKD) is a common hereditary renal cystic disease with an incidence of approximately 1:1000, which is mainly caused by mutations of the PKD1 or PKD2 genes." (PMID 27460786, 2016). "Autosomal dominant polycystic kidney disease (ADPKD) is the most common inherited kidney disorder mainly caused by mutation in PKD1/PKD2." (PMID 27782177, 2016). "Autosomal dominant polycystic kidney disease (ADPKD) is caused by mutations in the PKD1 or PKD2 gene." (PMID 26110849, 2015). "Autosomal dominant polycystic kidney disease (ADPKD), an inherited syndrome affecting 1∶400–1,000 individuals, arises from mutations in the PKD1 or PKD2 genes, encoding the polycystins." (PMID 25474361, 2014). "Polycystic liver disease (PLD) occurs in 75–90% of patients affected by autosomal dominant polycystic kidney disease (ADPKD), which affects 1∶400–1,000 adults and arises from inherited mutations in the PKD1 or PKD2 genes." (PMID 25474361, 2014). "Loss of PKD1 or PKD2 function in renal tubular epithelial cells causes Autosomal Dominant Polycystic Kidney Disease (ADPKD) that is the result of abnormal cell proliferation and cell polarity and leads to cystic kidney disease." (PMID 23029375, 2012). "Autosomal dominant polycystic kidney disease (ADPKD) is a commonly inherited renal disorder caused by defects in the PKD1 or PKD2 genes." (PMID 20169078, 2010). "The autosomal dominant polycystic kidney disease (ADPKD) is mostly caused by mutations in the PKD1 (polycystic kidney disease 1) gene located in 16p13.3." (PMID 18822117, 2008). "In autosomal dominant polycystic kidney disease (ADPKD), Pkd1 mutations cause PC-1 deficiency, leading to impaired mechanically induced Ca2+ influx, elevated cAMP levels, and PKA activation, thereby promoting tubular cell proliferation and cyst fluid secretion." (PMID 41602825, 2026). "Autosomal dominant polycystic kidney disease (ADPKD) shows remarkable variability in clinical severity, even among individuals with the same PKD1 or PKD2 pathogenic variants." (PMID 41502815, 2026). "PKD1 and PKD2 are the most commonly mutated genes in autosomal dominant polycystic kidney disease (ADPKD)." (PMID 41086943, 2025). "Autosomal dominant polycystic kidney disease (ADPKD), which is caused mainly by mutations in the PKD1 or PKD2 genes, is a genetic disorder characterized by the growth of cysts and decreased kidney function." (PMID 41254555, 2025). "Autosomal dominant polycystic kidney disease (ADPKD) is one of the most common single-gene inherited disorders, primarily resulting from mutations in the PKD1 gene (approximately 85%) or the PKD2 gene (approximately 15%)." (PMID 40308771, 2025).